CD4 (CD4 molecule)
Diseases named in the same sentence as CD4 in open-access papers (continued):
Sharing a sentence is not in itself a finding about the gene and the disease.
tumor (continued). "While CD8+ T-cell priming by TME-infiltrating DC has been studied, we still have a limited understanding of (i) how tumor-infiltrating DCs direct CD4+ TH-cell differentiation and (ii) the functional roles differentiated TH effector cells play in tumor progression." (PMID 30926808, 2019). "The presence, number, and functionality of CD4 T cells are important in multiple steps of the oncogenic pathway, including recognition of tumor antigens, development of effective neutralizing antibody, and cellular responses to viral pathogens, and clearance of premalignant lesions." (PMID 31555284, 2019). "However, the presence of several different subtypes of CD4+ T cells with opposing actions on anti-tumor activity in the tumor microenvironment has confounded the efforts to specifically induce CD4+ T cell responses for cancer immunotherapy." (PMID 31754392, 2019). "Notably, DP T cell were found to favor a Th2 polarization of CD4 T cells in vitro, at the expense of the protective Th1 functional profile known to play a crucial role in anti-tumor immunity." (PMID 30984190, 2019). "Further, tumor specific CD4+ T cells regulate the survival of CD8+ memory T cells." (PMID 31024545, 2019). "More recently, several studies highlighted anti-tumor properties of IL-9 producing CD4+ T cells." (PMID 31156634, 2019). "The combination therapy increased tumor-infiltrating CD4+ and CD8+ T cells in vivo." (PMID 31574081, 2019). "In order to better understand the important role of cryo-thermal therapy-induced macrophage re-education to the M1 phenotype in long-term anti-tumor immune memory, the percentages of splenic CD4+ T cells, CD8+ T cells, and their markers were analyzed by flow cytometry, respectively." (PMID 30833570, 2019). "In addition, several studies demonstrate that CD4 CTLs have the ability to directly kill tumor cells and eradicate established tumors in an MHC class II-dependent manner in mouse models." (PMID 31719197, 2019). "Our previous study demonstrated that the PEK protein vaccine is able to generate potent antigen-specific immunity, including antigen-specific CD8+ and CD4+ T cell precursors, antigen-specific Abs, and anti-tumor effects to control micro-metastatic tumor lesions in a pulmonary metastatic model." (PMID 31546897, 2019). "CD4+ T lymphocytes may eliminate tumor cells by cytolysis or by regulating the tumor microenvironment." (PMID 31612115, 2019). "Moreover, the gradual upregulation of ST2 on tumor-isolated CD4+ FOXP3+ Tregs during intestinal tumorigenesis suggested an immune regulatory function of IL-33 for this disease." (PMID 31165767, 2019). "In addition, 19305DP-TCR-transduced CD4+ T cells inhibited in vivo tumor growth at similar efficacy compared to CD8+ T cells engineered with the same TCR." (PMID 30626427, 2019). "Immunophenotyping of tumor-infiltrating lymphocytes in the second regression phase revealed significantly more cytotoxic (CD4−/CD8+) T-lymphocytes compared to peripheral blood, whereas percentages of the T-helper (CD4+/CD8−) lymphocytes and double-positive (DP) CD4+/CD8+ T-lymphocytes were reduced." (PMID 31717496, 2019). "We sorted GP66-specific T cells from dLN cells, because these were the only dLN CD4+ T cells for which tumor specificity could be ascertained." (PMID 31801070, 2019). "In addition, the percentage of Treg increased and the CD8+/Treg (CD4+FoxP3+) ratio was reduced in the residual tumor." (PMID 31780645, 2019). "Our studies of the protective efficacy of vaccination in mice challenged twice with B16-OVA tumor cells showed that suppression of challenged tumor growth was attributable to the increased infiltration of both CD4(+) and CD8(+) T lymphocytes into the tumor tissues." (PMID 31847372, 2019). "Interestingly, depletion of CD4+ T cells completely abrogated the anti-tumor efficacy of the class II HER2-DC1 alone or in combination with anti-PD-1 therapy suggesting the crucial role of CD4+ T cells." (PMID 31475002, 2019).
tumor (continued). "We set up a tractable experimental system to study tumor antigen-specific CD4+ T cells." (PMID 31801070, 2019). "Hence, proteobacteria ablation results in the immunogenic reprogramming of the tumor microenvironment through enhanced T helper-1 (TH1) differentiation of CD4+ and up-regulation of programmed cell death- 1(PD-1) expression." (PMID 31540435, 2019). "However, the mechanistic aspects of TRAPs in the modulation of immune cell function, especially the key anti-tumor effector cell, CD4+ T cell, in the tumor microenvironment and during tumor progression are unclear." (PMID 31300052, 2019). "Since IL-27 regulates the balance of Th1 and Th2 cells, it has the potential to skew the CD4+T cell response toward Th1, which could enhance tumor regression." (PMID 31681561, 2019). "Indeed, many evidences support that CD4+ Th1 subset orchestrates cell-mediated immunity against cancer cells mainly by enhance tumour-specific CD8+ T-cell functions, survival and migration in the TME." (PMID 31358938, 2019). "Therefore, GITR agonist and PD-1 blockade modestly increased the percentage of CD8+ T cells in the tumor and the addition of peritumoral DR-BMCs skewed the tumor CD4+ T-cell compartment towards an immune-stimulating response." (PMID 31747946, 2019). "On the other hand, tumor antigen-specific CD4+ T cells have been demonstrated to represent essential contributors of CTL-mediated tumor attack, implying that epitopes presented by MHC II molecules to CD4+ T cells are of central importance in tumor immune surveillance." (PMID 31519152, 2019). "Although depletion of Tregs could enhance the CD4+ T cell response to the vaccine cells, Tregs might also improve anti-tumor immunity by promoting the generation of CD8+ T memory cells via production of IL-10." (PMID 30956760, 2019). "Among the most important cells in tumor elimination are CD4+ T cells, particularly the Th1 subtype, whereas the CD4+ Tregs (regulatory T cells) subtype have been implicated in tumor progression and maintenance of a pro-tumor microenvironment by interfering in CD8+ T responses." (PMID 31762937, 2019). "In this study, we comprehensively investigated the potential roles of multiple CD4+ T cell cytokines (Th1, Th2, and Th17 cell cytokines) and Tregs as factors representing tumor status and predicting prognosis in patients with HCC treated by transarterial chemoembolization (TACE)." (PMID 30824840, 2019). "In line with this, it was shown that subverted CD4+ T cell subsets within the tumor microenvironment may exhibit a tumor-promoting activity." (PMID 31137912, 2019). "We hypothesized that PDATME DC facilitate tumor progression by inducing tolerogenic CD4+ or CD8+ T-cell differentiation." (PMID 30926808, 2019). "CD4+ is a T helper cell with the function of immune regulation, which can recognize the antigens produced by tumor and inhibit cancer cells by activating other immune cells, such as NK cells and cytotoxic T lymphocyte, and NK cells also play a role in activation of cytotoxic T cell." (PMID 31856760, 2019). "Successful immunity to cancer therefore requires activation of tumor-specific CD4 T cells." (PMID 31138124, 2019). "In a previous study we thus used HLA-DR4 transgenic (HLA-DR4tg) mice to identify the first NY-BR-1-specific CD4+ T cell epitopes that might help to induce and monitor tumor antigen-specific T cell responses in breast cancer patients." (PMID 31519152, 2019). "Additionally, tumor-infiltrating CD4+ T cells upregulated programmed cell death protein-1 (PD-1), cytotoxic T-lymphocyte-associated protein-4 (CTLA-4), T cell immunoglobulin and mucin domain-3 (TIM-3) and lymphocyte-activation gene 3 (LAG-3)." (PMID 31921188, 2019). "Furthermore, through elevated influx of APCs into the treated tumors, the CPMV in situ vaccine also facilitates priming of an adaptive anti-tumor response with CD4+/CD8+ cells, therefore leading to systemic efficacy and immunological memory." (PMID 30974896, 2019).
tumor (continued). "Cytotoxic CD8 T cells are Th1-differentiated CD4 T cells are the main drivers of anti-tumor immunity, and there is a strong clinical and experimental evidence that chemokines are necessary to for the recruitment of these cells into the tumor." (PMID 30873179, 2019). "The CD4/CD8 T cell ratio in untreated mice decreased markedly by day 28 after tumor inoculation." (PMID 31307539, 2019). "This may decrease the efficiency of the endocytosis of apoptotic and necrotic tumor cells by DCs, which may reduce antigen presentation that induces CD4+/CD8+ T cell-mediated anti-tumor immunity." (PMID 31921114, 2019). "Hence, CD4 T cells recognizing tumor neoepitopes contribute significantly to the efficacy of several types of immunotherapies in murine models and in cancer patients." (PMID 31273938, 2019). "Tumor-derived vesicles were found tosignificantly increase the expression of genes having a verifiedimmunity-regulating function in activated CD4+ T cells, while innaïve cells, gene expression slightly increased only for FAS1, IL-10, andPTGS2, while decreasing for DPP4, CD40LG, and NT5E." (PMID 31993233, 2019). "The role of different subsets of CD4+ T cells in tumor immunity remains underappreciated." (PMID 31412566, 2019). "First, we showed that high CD4 + T-cell density was associated with a positive outcome and was an independent prognostic factor in a multivariate model of CRC; it had greater prognostic value than tumour invasion depth or positive lymph node metastasis." (PMID 31488881, 2019). "In addition, more studies into the direct effects of CD4+ T cells on the tumor microenvironment and their contribution to the killing of cancer cells are needed." (PMID 31379821, 2019). "Besides killing directly MHC class II positive tumor cells, CD4+ T lymphocytes can indirectly eliminate cancer cells lacking of MHC class II, which is the most frequent condition in tumors, including PC, and in our PC-SLCs." (PMID 31366386, 2019). "The in vivo mechanism(s) by which these MHC class I-restricted CD4+ T cells mediate anti-tumor effects could be further investigated by in vivo blockade of IFN-γ, TNF-α or IL-2, or by using IFN-γR or TNF-αR knockdown cancer cells." (PMID 30626427, 2019). "CD8+ and CD4+ T cell activation induced by administration of TCL-loaded cDC1s contributes to reduced tumor progression and even remission of established tumors derived from the three cancer cell lines B16-OVA, B16/F10 and MC38, the latter two not expressing exogenous Ags." (PMID 30961656, 2019). "Moreover, under the influence of CD4+ Th1 and Th2 cells in tumor microenvironment, TIBs polarize into Be-1 cells that produce IFN-γ, IL-12, and TNF-α or Be-2 cells that produce IL-2, IL-4, TNF-α, and IL-6." (PMID 31662750, 2019). "Our study reveals a novel cellular and molecular mechanism of how tumor-derived extracellular vesicles regulate CD4+ effector T cell function and highlights TRAPs and their membrane-bound DAMPs as important therapeutic targets to reverse the immunosuppressive tumor microenvironment." (PMID 31300052, 2019). "Moreover, the treated mice showed significantly higher levels of CD3+ and CD4+ T cells in the tumor." (PMID 31588231, 2019). "These cells include CD4 FOXP3+ regulatory T cells (Tregs), tumor-associated macrophages (TAMs) and myeloid-derived suppressor cells (MDSCs); all these subsets are capable of inhibiting effector T cell anti-tumor immune response, although with different mechanisms." (PMID 31060225, 2019). "Moreover, transplantation of Akkermansia muciniphila into mice improved the therapeutic efficacy of the anti-PD-1 antibody in an IL-12-dependent manner by increasing the recruitment of CCR9+CXCR3+CD4+ T cell to the tumor site." (PMID 31443339, 2019). "These CD4+ tumor-infiltrating lymphocytes (TILs) were mostly CD4+CD45RO+ memory T cells." (PMID 31261914, 2019).
tumor (continued). "It is known that the presence of T cells in tumor tissue may impact the prognosis of the disease and that a lower CD4+/CD8+ ratio is correlated with less aggressive tumors." (PMID 31607931, 2019). "However, CD4+ iNKT cells are also capable of lysing tumor cells releasing cytotoxic effector molecules." (PMID 31354710, 2019). "Moreover, several studies have demonstrated that CD4 T cells mediate better anti-tumor effects than CD8 T cells, by partnering with NK cells." (PMID 31852498, 2019). "The tumor/DC fusion cell expresses the whole set of tumor antigens in the setting of costimulatory and MHC molecules and facilitates access of tumor antigens to endogenous and exogenous pathways of antigen presentation, resulting in the induction of both CD4 and CD8 T cells." (PMID 31065274, 2019). "ELISPOT assays showed that five mixtures of MHC II-restricted huCD20-derived peptides (huMHC II_Mix 1, huMHC II_Mix 2, huMHC II_Mix 4, huMHC II_Mix 5, and huMHC II_Mix 8) were able to stimulate IFN-γ production by CD4+ T cells isolated from mice injected with EL4-huCD20 tumor cells." (PMID 31494742, 2019). "Our observations suggest that tumor antigen-specific CD4+CD8+ double-positive T cells could be a useful source for obtaining therapeutic tumor antigen-specific TCR genes for TCR gene-engineering." (PMID 30626427, 2019). "Alternatively, autophagy may provide tumor cells with a survival advantage, protecting them against immunosurveillance by suppressing CD4+ and CD8+ T cells." (PMID 30678689, 2019). "Disease resolution was found to coincide with marked expansion of lymphocytes, including functional EBV epitope-specific CD8+ and CD4+ T-cells exhibiting reactivity against a range of latent and IE lytic antigens, which were also expressed in tumor biopsy material." (PMID 31736946, 2019). "Melanoma xenograft (B16F10 on C57BL/6 mice), treated with CUR and APG, showed a significantly diminished growth of tumor implants harboring an increased immune cell infiltration (CD4+, CD8+), a reduced expression of PD-L1 on tumor cells and significantly lower percentage of Ki-67+ cells." (PMID 30959898, 2019). "Notably, CD4+ TILs include Tregs, which suppress the tumor-killing activities of cytotoxic CD8+ TILs." (PMID 31771653, 2019). "Conversely, cDC1 provide efficient processing and cross-presentation of exogenous antigens on MHC I molecules to activate CD8+ T cells and TH1 cell responses as a response to tumor cells or intracellular pathogens and cDC2 are known to be inducers of CD4+ T cell responses." (PMID 31736936, 2019). "Additionally, peripheral CD8+ T-cell counts, CD3+ T-cell counts, CD19+ B-cell counts, and CD4/CD8 ratio all showed relationships with tumor response to carbon ion radiotherapy in patients with prostate cancer." (PMID 30971280, 2019). "Although not directly implicated in tumor cell killing, CD4+ lymphocytes importantly determine the course of anti-tumor immune response through the array of cytokines they secrete." (PMID 31555270, 2019). "A recent study suggested that a high frequency of PD-L1+ CD4+ CD25+ Tregs in the tumor microenvironment could increase the number of PD-1+ CD8 Tregs and induce a more lethal effect of TILs by PD/PD-L1 blockade therapy." (PMID 31464648, 2019). "Furthermore, co-incubation of CD4+ T-cells with tumor exosomes increased the levels of critical immunological factors such as CTLA-4, TGF-β, IL-10, and COX-2." (PMID 31181729, 2019). "In addition, the CD4+ or CD8+ T‐cell numbers were decreased in GIST patients with high PD‐L1 expression in their tumours, suggesting that the exhausted T cells occurred not only in the tumour microenvironment but also in the whole body." (PMID 30714229, 2019). "In addition, IFNγ production by effector CD4+ T cells facilitates anti-tumor reactivity by blocking neo-vascularization, directly inhibiting tumor cell proliferation and upregulating tumor-expressed MHC molecules that improve CTL recognition." (PMID 30956760, 2019).
tumor (continued). "An increase in S1PR1 in CD4+ T-cells promotes STAT3 activation and JAK/STAT3-dependent Treg tumor migration, whereas STAT3 ablation in T-cells diminishes tumor-associated Treg accumulation and tumor growth." (PMID 31480382, 2019). "Although recent scRNA-seq studies had shed light on the Treg component of CD4+ TILs, our study assessed the transcriptomes of both regulatory and conventional components, in the tumor itself, and in draining lymphoid organs." (PMID 31801070, 2019). "Also, preclinical and clinical studies have shown that CD4+ T cells can induce durable immune-mediated tumor control, and in some cases to an even larger extent than CD8+ T cells 7,70-72." (PMID 31754392, 2019). "Together, these results indicated that CPMV+CPA combination therapy induced the recruitment of innate immune cells in the primary tumor, increased the activation of dendritic cells, and induced tumor‐infiltrating CD4+ and CD8+ T cells to establish adaptive immunity." (PMID 31453050, 2019). "Radiation specifically increased the proportion of tumor infiltrating CD4+ T cells, including regulatory T cells in WT mice (Fig 4Biii-iv), with a reciprocal decrease in the proportion of tumor infiltrating CD8+ T cells, including effector subtypes (Fig 4Bii and data not shown)." (PMID 30726287, 2019). "CD3+ TILs in the central tumor area (p = 0.010), CD4+ TILs in the central tumor area (p = 0.045), CD8 + TILs in the central tumor area (p = 0.033), and CD8+ TILs in the invasive margin area (p = 0.004) showed significant differences between lVI(−) and LVI(+) patients." (PMID 31616592, 2019). "The functional role CD4+ T cells play in immunological tumor attack is complex." (PMID 30853959, 2019). "In addition, the levels of tumor-infiltrating Foxp3hiTbethi Tregs strongly correlated with the levels of infiltrating CD4+Tbet+ and CD8+Tbet+ cells." (PMID 30658697, 2019). "Similarly, accumulated CD4+CD25+FoxP3+ Tregs was also found in both peripheral bloods and tumor tissues in Epstein–Barr virus-associated GC." (PMID 30988066, 2019). "C. Absolute number per gram of CD4 and CD25 + CD4+ Tregs per gram of tumor." (PMID 31046839, 2019). "In addition, a recent study showed that self-antigens that are modified by citrullination on tumor cells can mediate potent anti-tumor CD4 T-cell responses." (PMID 31221199, 2019). "Thus, in NSCLC, tumour growth was associated with a decrease of circulating antitumor Th1 responses, but an accumulation of exhausted PD-1+/TIM-3+ CD4+ T cells." (PMID 31358938, 2019). "Furthermore, there was a significant increase in the relative proportions of T cells, CD4+ T cells, and NK cells in the HCS-EMT6 tumors compared to controls, and this was associated with tumor suppression." (PMID 31561459, 2019). "Here, we demonstrate that CD4+ T cells when incubated with tumor-derived exosomes from mutant (MT) KRAS non-small-cell lung cancer (NSCLC) cells, patient sera, or a mouse xenograft model, induce phenotypic conversion to FOXP3+ Treg-like cells that are immune-suppressive." (PMID 31635338, 2019). "It has been well-established that CD4+CD25+ Treg cells suppress anti-tumor immunity." (PMID 31244823, 2019). "In KPC tumor, the infiltrating T cells were predominantly CD4+ and majority of them expressed PD-1." (PMID 30959852, 2019). "Thus, scRNA-seq analysis of tumor-specific CD4+ T cells identifies an unsuspected diversity of transcriptomic programs in the TME and dLN." (PMID 31801070, 2019). "Another tumor protective mode of action brought about by CD4+ T cells might be functional M1 polarization of TAMs through MHC II restricted interaction." (PMID 30853959, 2019). "Although PD-L1-expressing malignant cells could be targeted by PD-L1-specific CD8+ cytotoxic T lymphocytes, it remains unclear whether CD4+ helper T lymphocytes (HTLs) recognize and kill tumor cells in a PD-L1-specific manner." (PMID 31221178, 2019). "A very crucial role of CD4+ T lymphocytes in development of tumor has been well established." (PMID 30997737, 2019).